EDNRB (endothelin receptor type B)
Diseases named in the same sentence as EDNRB in open-access papers (continued):
Sharing a sentence is not in itself a finding about the gene and the disease.
Waardenburg-Shah syndrome (13 papers, 2013 to 2025). Waardenburg-Shah syndrome (WSS) is a neurocristopathy characterized by the association of Waardenburg syndrome (sensorineural hearing loss and pigmentary abnormalities) and Hirschsprung disease. "Both frame overo patterning and Waardenburg-Shah syndrome are also associated with changes in iris color: humans and horses with EDNRB mutations often have blue eyes, and heterochromia is commonly observed." (PMID 34459920, 2021). "Within the Pakistani population, there is a high likelihood that mutations of the EDNRB gene are the causative mutation of Waardenburg syndrome type IV." (PMID 31998473, 2020). "In humans, mutations in EDN3 and EDNRB cause Waardenburg-Shah syndrome (Waardenburg syndrome type IV) hallmarked by defects in pigmentation and neonatal bowel obstructions." (PMID 24857848, 2014). "EDNRB encodes the endothelin B receptor; homozygous mutations cause Waardenburg syndrome type IV, while haploinsufficiency may lead to isolated iris hypopigmentation." (PMID 40978814, 2025). "Mutations in the human genes encoding the endothelin ligand-receptor pair EDN3 and EDNRB cause Waardenburg-Shah syndrome (WS4), which includes congenital hearing impairment." (PMID 39868048, 2025). "Type IV or Waardenburg-Shah syndrome is associated with mutations in either Sry BOXIO transcription factor (SOX10), at 22q13.1, Endothelin 3 (EDN3), at 20q13, or Endothelin Receptor Type B (EDNRB) on chromosome 13q22.321,22." (PMID 30854529, 2017).
glioblastoma (10 papers, 2013 to 2025). The most malignant astrocytic tumor (WHO grade IV). "In contrast, IL1RL1, TGFB2, GLI1, and EDNRB was over-expressed in classical, and desmoplastic medulloblastoma, and glioblastoma." (PMID 31973134, 2020). "The expression of EDNRB, HJURP and PDLIM4 genes were significantly different between glioblastomas and grade III gliomas (p<0.001, p=0.004 and p<0.001, respectively)." (PMID 24039914, 2013).
lung carcinoma (9 papers, 2018 to 2025). "The targeting of EDNRB and its associated signaling pathways could be serve as a potential therapeutic strategy for effectively managing lung cancer." (PMID 40014586, 2025). "For example, promoter hypermethylation of the EDNRB gene was found in several human tumors, including lung cancer." (PMID 34039311, 2021). "Aberrant methylation of the EDNRB gene was detected in 32.9% (26 of 79) of lung cancer patients, which then decreased EDNRB expression and contributed to tumor progression." (PMID 34039311, 2021). "In our query, EDNRB is shown to be co-expressed with BMP5 in bladder, breast, colorectal and lung cancer." (PMID 31973134, 2020). "EDNRB and HHIP in this pathway were found to be downregulated in this study, which is consistent with previous reports regarding patients with lung cancer." (PMID 33046043, 2020). "Furthermore, our study investigated the relationship between IPF-ARGs and lung cancer, identifying CDH3 as an oncogenic gene and recognizing EDNRB, MAOA, and PLA2G1B as tumor suppressor genes." (PMID 40589973, 2025).
prostate carcinoma (9 papers, 2002 to 2025). A carcinoma that arises from epithelial cells of the prostate gland. "For example, decreased expression of EDNRB in prostate cancer and triple-negative breast cancer is associated with tumor progression and poor prognosis." (PMID 40589973, 2025). "In this study, we constructed a model using a Cox proportional hazards model based on the expression of eight immune-related genes that were associated with prognosis in prostate cancer: EDNRB, ANGPTL2, TNFSF15, TNFRSF10D, EDN2, BMP2, NLRP14, and PLK1." (PMID 33197890, 2020). "Paradoxically, EDNRB overexpression inhibits proliferation and migration of prostate cancer cells through activation of the cGMP-PKG pathway." (PMID 40892354, 2025). "EDNRB CpG island hypermethylation was shown to be correlated with pathological stage and Gleason score to a statistically significant extent in prostate cancer." (PMID 24326135, 2013). "The extent of hypermethylation at CpG island in EDNRB gene was also evaluated in seven prostate cancer cell lines, normal prostate epithelial cells, normal prostate stromal cells, 73 primary prostate cancers, 91 metastatic prostate cancers, and 25 noncancerous prostate tissues." (PMID 24326135, 2013).
glioma (7 papers, 2008 to 2026). A benign or malignant brain and spinal cord tumor that arises from glial cells (astrocytes, oligodendrocytes, ependymal cells). "Endothelins (ET-1, ET-2, ET-3), vasoactive peptides mainly produced by vascular cells, signal through the G-protein-coupled receptors EDNRA and EDNRB and were previously suggested to promote glioma proliferation based on serum-based models." (PMID 42026941, 2026).
colorectal cancer (6 papers, 2013 to 2025). A primary or metastatic malignant neoplasm that affects the colon or rectum. "It has been reported that there was higher frequency of EDNRB hyper methylation in a sample of Iranian colorectal cancer tissues compared with normal margins." (PMID 33883026, 2021). "Similarly, the Chinese colorectal cancer tumors had significantly higher frequency of EDNRB promoter hyper methylation compared with normal tissues." (PMID 33883026, 2021). "The endothelin receptor type B (EDNRB) gene, a potential tumor suppressor gene, is vital for developing the enteric nervous system in the colon and is often silenced in colorectal cancer." (PMID 40141189, 2025). "To evaluate whether CAFs expressing Tr-CAF markers could inhibit tumor progression, we investigated the correlation between the CAF-specific immunohistochemical (IHC) staining levels for these 4 CAF markers; CXCL14, ADAMDEC1, EDNRB, and PROCR, and the clinical outcomes of colorectal cancer patients." (PMID 40759242, 2025).
deafness (6 papers, 2015 to 2022). An inherited or acquired condition characterized by the complete loss of the ability to hear from one or both ears. "In mouse models, both EDNRB spontaneously mutated and EDNRB homozygous knockout (EDNRB–/–) mice developed severe congenital deafness." (PMID 36311029, 2022). "EDNRB (OMIM entry 131244) is acted on by endothelin 3 to act on the MAPK pathway to act on posttranslational Mitf, and EDNRB mutations are associated with lethal white foal syndrome in horses and deafness in American Paint horses." (PMID 26664958, 2015). "EDNRB is probably responsible for deafness in lethal white foal syndrome and deafness in BEW American Paint and pinto horses." (PMID 26664958, 2015). "Phenotypes caused by the genes endothelin 3 (END3), endothelin receptor B (EDNRB), microphthalmia-associated transcription factor (MITF), paired box 3(PAX3), SRY-box 10 (SOX10), and snail homolog 2 (SNAI2) can result in decreased melanocytes, white coat color, and ultimately deafness." (PMID 27698666, 2016). "Across species, the genes identified with deafness or white pigmentation patterns include MITF, PMEL, KIT, EDNRB, CDH23, TYR, and TRPM1 in dog, cat, horse, cow, pig, sheep, ferret, mink, camelid, and rabbit." (PMID 26664958, 2015).
atherosclerosis (5 papers, 2015 to 2025). A disease characterized by the build-up of fatty material and calcium deposition in the arterial wall resulting in partial or complete occlusion of the arterial lumen. "Besides the SNPs on chromosome 9p21, endothelin receptor type B-rs5351 also is known to increase the risk of atherosclerosis in Japanese males (OR of the allele AA-GG = 5.0; CI = 1.13–2.04; p = 0.0187)." (PMID 28813480, 2017).
gastric cancer (5 papers, 2011 to 2024). A primary or metastatic malignant neoplasm involving the stomach. "EDNRB gene promoter methylation was shown to be associated with gastric cancer tumor invasion." (PMID 24326135, 2013). "Aberrant epigenetic methylation alterations of EDNRB expression play an important role in the pathogenesis of hepatocellular carcinoma and gastric cancer." (PMID 38205153, 2024). "Epigenetic alteration of EDNRB expression by aberrant methylation has an important role in the pathogenesis of hepatocellular carcinoma, and in gastric cancer." (PMID 32194414, 2020). "At first sight, this scenario was not in line with the literature notion, according to which silencing of EdnrB by aberrant methylation has an important role in the pathogenesis of hepatocellular carcinoma, and in gastric cancer." (PMID 32194414, 2020). "Hypermethylation of the EDNRB gene in paired gastric cancer tissues and adjacent normal tissues from 96 patients was detected." (PMID 24326135, 2013).
uveal melanoma (5 papers, 2002 to 2021). A melanoma derived from melanocytes of the uveal tract. "This is supported by the finding of a constitutively active GNAQ mutation in an NF1+/− uveal melanoma, which otherwise might be redundant, if EDNRB/GNAQ signaling completely overlapped with NF1." (PMID 23555837, 2013). "To investigate the underlying mechanism for reduced EDNRB expression in uveal melanoma, we examined whether the EDNRB gene on chromosome 13q22 was homozygously deleted." (PMID 12439722, 2002). "To determine whether EDNRB expression could be correlated to metastatic disease and to other prognostic indicators, such as clinico-pathological variables and genomic alterations (specifically chromosome 3 loss), we analysed EDNRB expression in a further 33 uveal melanomas by cmRT–PCR." (PMID 12439722, 2002). "Because oncogenic Gαq/11 mutations increase signaling, this is seems unexpected and contradictory if one assumes that EDNRB signals through Gαq/11 in uveal melanoma cells." (PMID 27148356, 2016). "Studies using smaller tumours, and uveal melanoma cell lines from tumours at different stages of progression, would go some way to determining at which stage down-regulation of EDNRB occurs." (PMID 12439722, 2002). "Our findings suggest a role for endothelin receptor type B in the metastasis of uveal melanoma and, potentially, in the metastasis of other neural crest tumours." (PMID 12439722, 2002). "In summary, we have shown that EDNRB shows reduced expression in large primary uveal melanomas of high metastatic genotype and phenotype, and in small cell lung cancer." (PMID 12439722, 2002). "It is important to point out that due to the lack of small tumours in this study, our observations concerning EDNRB down-regulation and metastasis cannot be applied to small T1 and T2 uveal melanomas." (PMID 12439722, 2002). "Although EDNRB mutations have not been identified in uveal melanoma, the loss of EDNRB expression in uveal melanoma has been correlated with a worse prognosis in two different studies." (PMID 27148356, 2016). "EDNRB and Gαq/11 may become unlinked in the situation of uveal melanoma." (PMID 27148356, 2016). "The role of EDNRB in both uveal melanoma and other cancers, therefore, remains unclear." (PMID 12439722, 2002). "We also show that the observed down-regulation of endothelin receptor type B in uveal melanoma was not due to gene deletion." (PMID 12439722, 2002). "In addition, it would be very interesting to correlate tumor progression with both EDNRB expression and the presence or absence of GNAQ and GNA11 mutations in uveal melanoma." (PMID 27148356, 2016). "We describe here the identification of endothelin receptor type B (EDNRB) as a gene that is differentially expressed between primary uveal melanomas of different metastatic status and demonstrate the differential expression of EDNRB in a wider uveal melanoma series." (PMID 12439722, 2002).
asthma (4 papers, 2007 to 2022). "In summary, the present study is the first report for a strong association between the EDNRB-30G>A polymorphism and the degree of airway obstruction, especially in patients with factors predisposing to airway remodelling such as asthma or smoking." (PMID 17470272, 2007). "the EDNRB-30G>A polymorphism could be a determinant of airway obstruction in humans with predisposing factors such as tobacco smoke exposure or asthma." (PMID 17470272, 2007). "Many of the upregulated genes in nicotine-treated sperm are known to be involved in asthma pathogenesis, including L-Histidine decarboxylase (Hdc), Fc receptor-like 3 (Fcrl3), Endothelin receptor type B (Ednrb), and Complement C4A (C4a)." (PMID 35600600, 2022).
cutaneous melanoma (4 papers, 2002 to 2022). A primary melanoma arising from atypical melanocytes in the skin. "A comparison of EDNRB in four cutaneous melanoma cell lines originating from metastases, with three cell lines from primary tumours has shown the metastatic tumours to be characterised by low level expression of EDNRB." (PMID 12439722, 2002). "However, the dual EDNRA/EDNRB antagonist, Bosentan, was tested in phase II clinical trials and failed to produce a robust response in cutaneous melanoma patients, neither alone nor in combination with dacarbazine." (PMID 35158973, 2022).
enterocolitis (4 papers, 2014 to 2019). An inflammatory process affecting the small intestine and colon. "A previous study on EDN3 and EDN receptor type B (EDNRB) knockout mouse model showed that EDN3 and EDNRB were associated with severe enterocolitis." (PMID 31167651, 2019). "EdnrB was deleted from the neural crest (EdnrBNCC-/-) resulting in mutants with defective NCC migration, distal colonic aganglionosis and the development of enterocolitis." (PMID 26061883, 2015).
glaucoma (4 papers, 2013 to 2023). Increased pressure in the eyeball due to obstruction of the outflow of aqueous humor. "EDNRB was an injury response susceptor of Müller cells, and it was sensitive for hyperglycaemia, glaucoma, and ischemic retinopathy." (PMID 36418970, 2022). "Multiple cell types in the retina and optic nerve express EDNRA and EDNRB and thus could respond to EDN ligands in the context of glaucoma." (PMID 35429992, 2022).
hearing loss (4 papers, 2011 to 2025). "EDNRB expressed in SGNs could be a novel potential therapeutic strategy for congenital hearing loss in WS-IV patients." (PMID 22899349, 2013). "Therefore, targeted modulation of EDNRB expression in SGN might be a new strategy to treat congenital hearing loss patients with WS-IV." (PMID 36311029, 2022). "Most importantly, 27 GPCRs were found to be associated with hearing loss, 5 of which were directly associated with human hearing disorders (VLGR1, mGluR7, V2R, EDNRB, and S1PR2)." (PMID 36311029, 2022). "Thus, our results indicate that c-RET and EDNRB expressed in SGNs could be molecular targets in the prevention of hearing impairments." (PMID 22899349, 2013).
hepatocellular carcinoma (4 papers, 2017 to 2024). A malignant tumor that arises from hepatocytes. "Higher EDNRB expression correlates with reduced immune cell infiltration and poorer prognosis in hepatocellular carcinoma patients." (PMID 39006665, 2024). "EDNRB (endothelin receptor type B) has been shown to promote immunosuppression in hepatocellular carcinoma." (PMID 39006665, 2024). "Notably, EDNRB has been found to inhibit proliferation and migration in lung cancer cell line H1299, exhibit lower expression levels in hepatocellular carcinoma compared to adjacent tissues, and its hypermethylation reduces expression in oral squamous cell carcinoma lesions." (PMID 38205153, 2024). "Further, epigenetic alterations of the EDNRB gene, a target of SOX10, might play an important role in the pathogenesis of hepatocellular carcinoma." (PMID 28347313, 2017).
leukemia (4 papers, 2009 to 2023). A malignant (clonal) hematologic disorder, involving hematopoietic stem cells and characterized by the presence of primitive or atypical myeloid or lymphoid cells in the bone marrow and the blood. "In addition, we detected repression of the EDNRB gene in BMMCs exposed to malathion, which suffers hypermethylation in different types of leukemia." (PMID 37047231, 2023).
Obesity (4 papers, 2014 to 2025). Accumulation of substantial excess body fat. "Association between obesity and BMI and SNPs of EDNRB genes adjusted by age and sex in: A-Valcar Study / B-Hortega Study / C-Both." (PMID 25799405, 2015). "Haplotype association analysis of rs5351 and rs3759475 of EDNRB gene with BMI and obesity risk adjusted by age and sex in relation with Arsenic serum levels." (PMID 25799405, 2015). "Of all the polymorphisms, only two located in the EDNRB gene (rs5351 and rs3759475) were associated with obesity." (PMID 25799405, 2015). "Haplotype association analysis of rs5351 and rs3759475 of EDNRB gene with BMI and obesity risk adjusted by age and sex." (PMID 25799405, 2015). "Genetic variants in NO synthase and EDN isoforms and its receptors (EDNRA and EDNRB) appear to account for important components of the variance in ED, particularly when concurrent risk factors such as obesity exist." (PMID 24410812, 2014). "We have found an association for two polymorphisms of the EDNRB gene with obesity." (PMID 25799405, 2015). "Our results support the hypothesis that polymorphisms of the EDNRB gene may influence the susceptibility to obesity and can interact with plasma arsenic levels." (PMID 25799405, 2015). "In addition, it has been described that inhibition of EDNRB protects lipid droplets against the effect of arsenic, which can be associated with the development of obesity." (PMID 25799405, 2015). "Thus, our results indicate that elevated arsenic levels modulate the EDNRB association with obesity." (PMID 25799405, 2015). "In conclusion, our study carried out in two Spanish populations from different regions and noticeably distinct characteristics supports the hypothesis that polymorphisms of the EDNRB gene may influence the susceptibility to obesity." (PMID 25799405, 2015). "The possible role of SNPs of the EDNRB gene in obesity phenotypes should be confirmed by other studies, including analyses among different populations, larger sample sizes, etc." (PMID 25799405, 2015). "We found associations for two polymorphisms of the EDNRB gene which codifies for EDN receptor type B. Genotypes AG and AA of the rs5351 were associated with a lower risk for obesity in the VALCAR sample (p=0.048, OR=0.63) and in the Hortega sample (p=0.001, OR=0.62)." (PMID 25799405, 2015).
Right ventricular hypertrophy (4 papers, 2014 to 2024). In this case the right ventricle is more muscular than normal, causing a characteristic boot-shaped (coeur-en-sabot) appearance as seen on anterior- posterior chest x-rays. "Rats with right ventricular hypertrophy had a decreased expression of the endothelin-B receptor (EDNRB) in the lung, together with an increased protein content of endothelin-1 and an increased expression of ACTA2A." (PMID 39452062, 2024).
cardiac hypertrophy (3 papers, 2017 to 2019). "It contributes to a reduction in cardiac output, the stimulation of cardiac hypertrophy, and fibroblast proliferation by activating two G-protein–coupled receptors: endothelin receptor type A (ETA) and endothelin receptor type B (ETB)." (PMID 31766450, 2019).
cervical cancer (3 papers, 2009 to 2020). A primary or metastatic malignant neoplasm involving the cervix. "The rate of ESR1 and EDNRB mutation was 6 and 7% in cervical cancer." (PMID 32368784, 2020). "In our study, we found that ESR1 and EDNRB expression levels were lower in cervical cancer samples than in the normal samples." (PMID 32368784, 2020). "Endothelin receptors A and B (EDNRA, and EDNRB) have altered expression levels in multiple cancers, such as colorectal, bladder, prostate, and nasopharyngeal carcinomas, in addition to cervical cancer." (PMID 30020984, 2018). "Ten genes validated with the TCGA database, including five DMGs (ESR1, EPB41L3, EDNRB,ID4, PLAC), might be used as biomarkers and therapeutic targets in the precise diagnosis and treatment of cervical cancer." (PMID 32368784, 2020).